RNU7-45P (RNA, U7 small nuclear 45 pseudogene)
Synonyms: U7.45
Gene: Small nuclear RNA gene on chromosome 2 (201,141,904 to 201,141,966, forward strand). Ensembl gene ENSG00000238829.
Homologues: Orthologues: chimpanzee U7 (100% identical), macaque U7 (97% identical). Paralogues in human: RNU7-13P (90% identical), RNU7-18P (89% identical), RNU7-28P (89% identical), RNU7-6P (89% identical), RNU7-11P (87% identical), RNU7-128P (87% identical), RNU7-23P (87% identical), RNU7-14P (86% identical), RNU7-22P (86% identical), RNU7-40P (86% identical), RNU7-7P (86% identical), RNU7-85P (86% identical), and 142 more.